INS (insulin)
Diseases named in the same sentence as INS in open-access papers (continued):
Sharing a sentence is not in itself a finding about the gene and the disease.
diabetic ketoacidosis (continued). "However, only a few cases of diabetic ketoacidosis (DKA) with longitudinal evaluation of endogenous insulin secretion related to TAC administration have been reported." (PMID 31490380, 2019). "Acidosis in diabetic ketoacidosis patients might be due to the contribution of vitamin D in insulin secretion and improving insulin sensitivity." (PMID 31259115, 2019). "However, after the initial treatment for diabetic ketoacidosis, his insulin secretion was found to be normal and the plasma levels of ketones were not elevated." (PMID 30609924, 2019). "Whether this finding is due to sampling bias, the incidence of diabetic ketoacidosis or related to the insulin preparation, i.e. pharmacological properties and half-life of insulin applied as bolus (MDI) or continuously (CSII), remains to be elucidated." (PMID 29311586, 2018). "Impact of insulin administration routes on diabetic ketoacidosis." (PMID 28659865, 2017). "Diabetic ketoacidosis was treated with intravenous fluid-electrolyte and insulin therapy." (PMID 28588004, 2017). "In early pregnancy, there is a decrease of exogenous insulin requirement, and throughout pregnancy a lower than expected incidence of diabetic ketoacidosis despite a fall in serum bicarbonate levels and accelerated maternal lipolysis and ketosis in later pregnancy." (PMID 28090333, 2017). "While we did not measure the plasma ketones, the phenotypic change of Cpt1b+/− mice is likely not due to diabetic ketoacidosis, because ketoacidosis should have caused systemic effects rather than skeletal muscle-specific insulin resistance." (PMID 25580367, 2014). "A potentially lethal complication of diabetic ketoacidosis (DKA) in children is brain oedema, whether caused by DKA itself or by the therapeutic infusion of insulin and fluids." (PMID 20723227, 2010). "The goal of screening and monitoring programmes is to reduce the adverse clinical consequences of diabetic ketoacidosis at diagnosis and to identify children who may benefit from disease-modifying therapies to delay or reverse progression to insulin requirement." (PMID 40988096, 2025). "The goal of this study was to determine if early insulin glargine administration (within six hours of starting insulin infusion) decreased the duration of insulin infusions and hospital stay versus the standard administration of insulin glargine in patients admitted with diabetic ketoacidosis." (PMID 40978981, 2025). "A patient with diabetic ketoacidosis might have normal potassium levels before the initiation of treatment; the medical practitioner should take caution to prevent severe hypokalemia after initiating insulin therapy." (PMID 37363479, 2023). "Indeed, to prevent the potentially dangerous complications associated with diabetes ketoacidosis, patients in treatment with SGLT2 inhibitors who develop the event should discontinue the medication, undergo ketone evaluation, and start insulin therapy, if blood ketones are detected." (PMID 35337085, 2022). "Also note the rapid resolution of diabetic ketoacidosis (DKA) with insulin therapy." (PMID 31259114, 2019). "Finally, the modalities of insulin therapy during diabetic ketoacidosis, the indications for sodium bicarbonate infusion and extra-renal purification as well as the modalities of mechanical ventilation during severe metabolic acidosis are addressed in therapeutic management." (PMID 31418093, 2019). "Diabetic ketoacidosis requires intravenous fluid replacement, insulin injection, correction of electrolyte imbalance, and possible bicarbonate administration in patients with severe acidosis, as well as prompt treatment for its etiology such as infection or insufficient insulin administration." (PMID 29258472, 2017). "He received standard treatment for a working diagnosis of diabetic ketoacidosis (DKA), improved clinically, and was discharged after five days, but continued to require exogenous insulin to maintain appropriate fasting and postprandial blood glucose levels." (PMID 42281726, 2026).
diabetic ketoacidosis (continued). "At age 12 years, she presented with diabetic ketoacidosis and was diagnosed with CFRD, requiring insulin therapy." (PMID 42022521, 2026). "Initial management of diabetic ketoacidosis (DKA) often involves administration of regular insulin, and the transition from regular to intermediate or long-acting insulin can be challenging." (PMID 42254904, 2026). "After correction of the initial diabetic ketoacidosis (DKA), insulin pump treatment was started while staying on MAD." (PMID 40135138, 2025). "A diagnosis of diabetic ketoacidosis (DKA) was made, and the patient commenced on normal saline 3 L to run for 12 hours, insulin soluble 18 IU in normal saline, insulin 7 IU subcutaneous hourly, and ceftriaxone IV OD." (PMID 40760593, 2025). "A Japanese case report described a CEL mutation in exon 2 (c.146_147delCT; p.Ser49CysfsTer52) in a 13-year-old girl presenting with her first episode of diabetic ketoacidosis (DKA) and impaired insulin secretion." (PMID 41153735, 2025). "A rare complication of pancreatic cancer is diabetic ketoacidosis (DKA), which arises from the tumor’s impairment of insulin production." (PMID 40443601, 2025). "Following her confirmed diagnosis, the patient experienced recurrent episodes of diabetic ketoacidosis (DKA), all attributable to suboptimal adherence to insulin therapy." (PMID 41367451, 2025). "He presented with polydipsia and polyuria following a fever post-vaccination, and was diagnosed with diabetic ketoacidosis (DKA), managed with insulin infusion." (PMID 41295485, 2025). "The aim of this work was to describe the phenotype of adults presenting with a first episode of diabetic ketoacidosis (DKA) in Cape Town, South Africa, and identify predictors of insulin independence at 12 and 60 months after presentation." (PMID 38240751, 2024). "The traditional treatment approach to diabetic ketoacidosis (DKA) involves the replacement of fluid and electrolyte deficits and a continuous intravenous infusion of regular insulin." (PMID 39130949, 2024). "The proband in Case 1 presented to us during adolescence with classic features of diabetic ketoacidosis, favoring a diagnosis of T1DM, and was started on insulin therapy." (PMID 39420905, 2024). "COVID-19: Coronavirus disease 2019, IV: Intravenous, RHI: Regular human insulin, subQ: Subcutaneous, DKA: Diabetic ketoacidosis, ICU: Intensive care unit, AKI: Acute kidney injury." (PMID 36741601, 2023). "Case 1 presented with diabetic ketoacidosis and was diagnosed with ICI-related diabetes mellitus and treated with insulin." (PMID 37732122, 2023). "It has been reported that diabetic ketoacidosis occurs in patients with T2DM who use GLP-1RA and insulin at the same time when the simultaneous use of insulin is rapidly reduced or stopped." (PMID 35865956, 2022). "In the overall, the appropriate management of diabetic ketoacidosis (DKA), consisting of overlapping the I.V and S.C insulin was performed by 29.6% of the participants." (PMID 35609030, 2022). "Poor blood sugar control due to inappropriate or absent insulin administration will lead to high blood sugar values that can lead to diabetic ketoacidosis (DKA)." (PMID 41597086, 2026). "Notably, following the initial launch of the GLP-1 RA liraglutide in Japan, cases of diabetic ketoacidosis (DKA) and mortality were reported in insulin-dependent individuals who discontinued insulin therapy upon switching to liraglutide." (PMID 40607140, 2025). "It is important to note that the pathophysiology of diabetic ketoacidosis is well known and is characterized by a relative or absolute lack of insulin and by an excess of counterregulatory hormones such as corticosteroids, glucagon, and catecholamines." (PMID 38899266, 2024).
diabetic ketoacidosis (continued). "The patient in Case 3 (a 14-year-old boy) had a variation in the KCNJ11 gene (MODY 13) and presented with diabetic ketoacidosis; after initially being treated as having T1DM, he developed progressive weight gain, acanthosis nigricans, and decreased requirement of insulin." (PMID 39420905, 2024). "Participant B similarly had a patient with diabetic ketoacidosis who became severely ill because the parents were praying that God would heal her without the need for insulin." (PMID 37953929, 2023). "One patient had a non-related SAE (diabetic ketoacidosis) due to non-compliance with insulin treatment." (PMID 38100463, 2023). "In a cross-sectional review, 41% of patients with MIDD were classified as non-insulin dependent, whereas 13% required insulin from the time of diagnosis and 8% presented in diabetic ketoacidosis." (PMID 35552684, 2022). "While diabetic ketoacidosis (DKA) is of theoretical concern on CSII given the sole use of rapid-acting insulin, recent studies do not demonstrate significant differences in rates of DKA between CSII and MDI." (PMID 37745178, 2021). "International and US guidelines also recommend treatment with insulin if glycaemic goals are not met or if the initial HbA1c is ≥8.5%, or in the presence of acidosis and/or diabetic ketoacidosis and/or other metabolic complications." (PMID 33634589, 2021). "The use of rapid-acting insulin analogs as routes of administration other than IV has never been described for the treatment of dogs with diabetic ketoacidosis (DKA)." (PMID 33195532, 2020). "R3.1—Insulin should probably be administered intravenously rather than subcutaneously in patients with diabetic ketoacidosis (GRADE 2+, STRONG AGREEMENT)." (PMID 31418093, 2019). "R3.2—An insulin bolus should probably not be administered before starting continuous intravenous insulin therapy in patients with diabetic ketoacidosis (GRADE 2−, STRONG AGREEMENT)." (PMID 31418093, 2019). "Specifically, sex, BMI, insulin treatment at the time of enrolment into UK Biobank, and diabetic ketoacidosis as a discharge diagnosis were not different between the groups." (PMID 29199115, 2018). "Insulin was used for the total duration of 8 days until TG level decreasedbelow 300 mg/dL, and unlike diabetic ketoacidosis, the patient was not bridged withsubcutaneous insulin therapy." (PMID 30186885, 2018). "Despite the high incidence of diabetic ketoacidosis (DKA) there is no consensus on the most appropriate way to manage insulin therapy." (PMID 30544554, 2018). "Most hospital admissions of T1D occur as a result of diabetic ketoacidosis, a condition of overly high level of ketone bodies, which is a direct consequence to a body’s lack of insulin." (PMID 28143555, 2017). "Our findings are robust and demonstrate that blood ketone levels are unrelated to blood glucose levels or insulin treatment in the critically ill diabetic patient without diabetic ketoacidosis within the boundaries of a liberal glucose protocol." (PMID 27633987, 2016). "In conclusion, diabetic ketoacidosis could be the first manifestation of LADA, although unusual, and should be treated with insulin." (PMID 25834574, 2015). "Hence, according to Chowdhury and Chakraborty, this most probably demonstrates diabetic ketoacidosis which usually appears in more than 90% of T1DM cases when they do not take exogenous insulin." (PMID 40365185, 2025). "In addition, although participants with β-cell failure had below normal insulin secretion, insulin secretion was still present, and no study participants reported a current or past history of diabetic ketoacidosis." (PMID 36211668, 2022). "Numerous studies suggest treating patients with subcutaneous insulin rather than intravenous insulin for uncomplicated, moderate diabetic ketoacidosis may be safer and more cost-effective." (PMID 36439560, 2022).
diabetic ketoacidosis (continued). "The most common complications were diabetes ketoacidosis after initiation of insulin therapy (diabetic ketoacidosis prior to diagnosis is not included here) (50%), bladder, yeast or other urinary tract infection (46%), stomach or intestinal problems (39%) and retinopathy (36%)." (PMID 33407910, 2021). "However, we can identify at least 4 precipitating factors of diabetic ketoacidosis in the previous case report, that are absent in our case report, such as: decreased oral intake, dehydration, no insulin treatment and oral corticosteroid treatment." (PMID 34281618, 2021). "When insulin was not administered, frequent episodes of diabetic ketoacidosis occurred." (PMID 32982980, 2020). "In addition, our patient has not developed diabetic ketoacidosis in the 15 years of her remission despite no insulin treatment." (PMID 24909320, 2014). "Ketosis-prone diabetes (KPDM) is new-onset diabetic ketoacidosis without precipitating factors in non-type 1 diabetic patients; after management, some are withdrawn from exogenous insulin, although determining factors remain unclear." (PMID 25275325, 2014). "In addition, while no cases of euglycemic diabetic ketoacidosis (euDKA) were observed in this study, the potential for euDKA—particularly in insulin-treated patients—has been described in human medicine and should be considered when using SGLT2 inhibitors clinically." (PMID 40796840, 2025). "Moreover, the diagnosis of adult-onset T1D is complicated by the high incidence of T2D in this age group, with a disease progression that is slower and less likely to present with diabetic ketoacidosis, or for insulin treatment to be initiated at onset irrespective of probable type." (PMID 37610700, 2023). "Total duration of diabetic ketoacidosis (DKA) and length of stay in episodes with vs. without fixed rate intravenous insulin infusion rate reduction by 50% initial rate when blood glucose <14 mmol/L during DKA across hospital sites A–E." (PMID 39928758, 2025). "Diabetic ketoacidosis (DKA) is a serious condition where high blood sugar and a lack of insulin lead to the buildup of acids called ketones in the blood." (PMID 39130871, 2024). "Because of the absence of endogenous insulin production, individuals with T1DM require exogenous insulin to prevent diabetic ketoacidosis (DKA), even in situations wherein glucose levels are not elevated." (PMID 31866948, 2019).
chronic kidney disease (316 papers, 2004 to 2026). Impairment of the renal function secondary to chronic kidney damage persisting for three or more months. "Acute metabolic acidosis (MA), a feature mostly associated with chronic kidney disease, decreases glucose tolerance and insulin sensitivity." (PMID 41634125, 2026). "For safety outcomes, DPP4is were associated with a reduced risk of chronic kidney disease, while insulin use was associated with reduced risks of inflammatory polyarthritis and insomnia." (PMID 40836299, 2025). "Chronic renal failure and liver cirrhosis were initially considered the primary causes of glucose fluctuations, given that both conditions impair insulin metabolism and hepatic glucose output." (PMID 41234224, 2025). "Elevated urea levels affect organ function and the course of chronic renal disease by causing carboxylation, insulin resistance, reactive oxygen species (ROS) generation, and inflammation." (PMID 40535386, 2025). "Insulin-secreting defects associated with chronic kidney disease arise from elevated circulating levels of urea that increase islet protein O-GlcNAcilation and alter glycolysis." (PMID 38892526, 2024). "Other factors heightening the risk of arrhythmia recurrence are history of chronic kidney disease and intensive insulin therapy, elevated WBC and serum creatinine levels, longer QTc in ECG, higher number of PVCs, and minimal heart rate in Holter monitoring." (PMID 39459449, 2024). "Insulin treatment was more associated with chronic kidney disease stages 4-5 (adjusted odds ratio (aOR) 2.41, 95% CI 1.07-5.43), retinopathy (aOR 3.10, 95% CI 1.04-9.27), and podiatry review (aOR 5.06, 95% CI 1.20-21.38)." (PMID 37152098, 2023). "What are the possible mechanisms for an association between insulin sensitivity and chronic kidney disease?" (PMID 29855339, 2018). "Among patients with chronic renal failure treated with hemodialysis, moderate to severe anemia was also a risk factor for insulin resistance." (PMID 28739553, 2018). "Obesity and T2D are associated with a higher risk of cardiovascular disease (CVD), decreased insulin sensitivity and chronic kidney disease (CKD), which increases mortality beyond the traditional CVD risk factors." (PMID 28805484, 2017). "Whereas failed adenosine uptake due to deficiency of insulin was recognized in our diabetic model, the mechanism leading to chronically high adenosine levels in these other models of chronic kidney disease remain to be determined." (PMID 28842605, 2017). "Also, elevated circulating levels of urea in chronic kidney disease can cause the dysfunction of secretory insulin." (PMID 32513106, 2020). "Insulin secretory defects have been found to be associated with human chronic kidney disease arising from elevated circulating levels of urea that may increase islet protein O-GlcNAcylation and impair glycolysis." (PMID 32317707, 2020). "Recent studies have identified specific uremic toxins that could mediate an association between chronic renal disease and insulin sensitivity, toxins such as p-cresyl sulfate a protein in the intestinal microbiota." (PMID 29855339, 2018). "Chronic kidney disease (CKD) is associated with decreased anabolic response to insulin contributing to protein-energy wasting." (PMID 36270479, 2023). "Besides, many studies had shown that a higher TyG index is associated with a higher risk of microalbuminuria and chronic kidney disease, which may be due to changes in renal endothelial function and hemodynamics caused by the reaction of insulin resistance." (PMID 34461808, 2021). "It is a metabolic disorder resulting from the relative deficiency of insulin production and/or its action, which leads to increased serum glucose levels, which is considered the main cause of chronic kidney disease (CKD)." (PMID 32130282, 2020).